EGFR (epidermal growth factor receptor)
Diseases named in the same sentence as EGFR in open-access papers (continued):
Sharing a sentence is not in itself a finding about the gene and the disease.
glioblastoma (continued). "Eighty patients showed glioblastoma (GBM)-like features: IDH1 and 2 wild types (wt) and imbalance of chromosome 7 and chromosome 10q loss of heterozygosity, or telomerase reverse transcriptase (TERT) promoter mutation, or epidermal growth factor receptor (EGFR) amplification." (PMID 36176387, 2022). "Glioblastomas cells with mutant IDH1, IDH2, and CpG island methylator phenotype (CIMP) showed remarkable alteration in the expression of variant genes, including WNT, epidermal growth factor receptor (EGFR), transforming growth factor-β (TGFβ), RAS, and angiogenesis-related genes." (PMID 36286449, 2022). "(A) Representative images shown as maximum intensity projection of DNA FISH for EGFR (red) in the nuclei of E26 (top) and E28 (bottom) glioblastoma (GBM) cell lines, scale bar = 1 μm." (PMID 36476408, 2022). "CAR T-cells targeting the epidermal growth factor receptor (EGFR) 806 epitope that is uniquely expressed on the surface of tumor cells can effectively eradicate glioblastoma (GBM) cells while sparing EGFR-expressing human fetal astrocytes." (PMID 35155252, 2022). "However, EGFR-targeted therapies brought poor results in patients with glioblastoma." (PMID 35214064, 2022). "The remaining tumours which lack IDH mutations are termed IDH wildtype glioblastoma (GBM) and are most often associated with TERT promoter mutations, gains of chromosome 7/EGFR, and loss of chromosome 10, characteristic of high grade (grade 4) GBM." (PMID 35526077, 2022). "However, the role of chromatin interactions and its regulation of gene expression in EGFR-amplified glioblastoma remains unclear." (PMID 35521558, 2022). "In addition to being effective in combination with conventional cancer treatment remedies, DSK and other shikonin derivatives have been shown to bind to EGFR kinase domain and to halt EGFR phosphorylation, thereby boosting the efficacy of an EGFR antagonist, erlotinib, on glioblastoma treatment." (PMID 35806120, 2022). "Moreover, in IDH-wildtype diffuse astrocytic gliomas the presence of one or more of three genetic parameters (EGFR gene amplification, TERT promoter mutation, 7+/10−) appears to be adequate to assign the highest CNS WHO grade and classify them as glioblastoma-wildtype." (PMID 34638714, 2021). "Therefore we examined whether oxelaidin is effective in inhibiting chemoresistance of glioblastoma cell lines, including constitutively active EGFR vIII-expressing U87MG (U87MG-vIII), temozolomide-resistant U87MG (U87MG-TMZR) and high MGMT-expressing T98G." (PMID 33980886, 2021). "Glioblastoma exhibiting activated EGFR signalling also showed the activation of Src and Fyn, which indicates that Src and Fyn inhibition may improve the efficacy of anti-EGFR targeted therapy." (PMID 34238111, 2021). "In glioblastoma cells, the EGFR tyrosine kinase activity may be dysregulated by multiple oncogenic mechanisms, such as gene mutation, overexpression of EGFR protein, increased gene copy number, rearrangements of chromosomes, and activation by autocrine function." (PMID 33435537, 2021). "The impact of tumor size on ADC tumor delivery and treatment response was evaluated in an EGFR-amplified patient-derived glioblastoma (GBM) model following treatment with Depatuxizumab mafadotin (Depatux-M)." (PMID 34549181, 2021).
glioblastoma (continued). "In addition, it should be noted that IDH-wild-type diffuse astrocytic tumors in adults, if microvascular proliferation or necrosis or TERT promoter mutation or EGFR gene amplification or +7/−10 chromosome copy number changes are present, should be diagnosed as IDH-wild-type glioblastoma." (PMID 35153659, 2021). "In addition, miR-148 regulates EGFR activity by targeting Gene 33 in glioblastoma." (PMID 34206547, 2021). "FPR1, in malignant glioblastoma multiforme (GBM) cells, is activated by the endogenous chemotactic ligand annexin 1 (ANXA1) released by necrotic GBM cells and functionally interacts with the EGFR to promote survival and invasiveness of GBM cells." (PMID 33923400, 2021). "Therefore, detecting the EGFR aberration status could help classify the molecular subtypes and predict treatment response and prognosis in glioblastoma patients." (PMID 34648115, 2021). "In additional to EGFR amplification/mutation, PTEN loss, and other mutational mechanisms, this may provide an additional mechanism for partial growth factor independence in glioblastoma." (PMID 34624316, 2021). "In addition to elevating oncogene levels by copy number amplification, ecDNA may re-integrate into HSRs of chromosome and/or affect DNA accessibility to further “stabilize” the expression of oncogenes (e.g. EGFR in glioblastoma)." (PMID 33902601, 2021). "However, the prognostic value of LANCL2 and EGFR co-amplification, and their mRNA and protein expression in glioblastoma remain unclear yet." (PMID 34461927, 2021). "Interestingly, overexpression of EGFR vIII is observed in 50–60% of EGFR-amplified glioblastomas." (PMID 34582442, 2021). "Moreover, our SCNA analysis revealed an increase in focal gains of EGFR with age in low-grade glioma but not in glioblastoma, suggesting differences in the age-associated genomic landscape between the two glioma types." (PMID 33879792, 2021). "One hypothesis that arises in light of these results is that, in cervical cancer, there may be a positive feedback loop, in which EGFR positively regulates uPA expression, and that its receptor, uPAR, may favor EGFR transactivation, as has been shown in glioblastoma." (PMID 33886813, 2021). "Similarly, miR-1238 was significantly enriched in the serum of glioblastoma patients compared to healthy individuals, and loss of miR-238 may lead to the formation of drug-resistant glioblastoma via the CAV1/EGFR pathway." (PMID 33313406, 2020). "Although targeted therapy has been successful in the treatment of cancers such as EGFR- or anaplastic lymphoma kinase (ALK)-mutated non-small-cell lung cancer or BRAFV600E-mutated melanoma, targeting these mutations has been largely ineffective in glioblastoma." (PMID 33396284, 2020). "By the presence of TERTp mutations, EGFR highcopy amplification and/or combined gains or losses of whole chromosome 7 and 10 these tumors could be reclassified as diffuse astrocytic gliomas, IDH-wildtype, with molecular features of glioblastoma." (PMID 32758285, 2020). "However, the results of these reports are similar to that found in our study and suggest that down-regulated miRNA-7 expression is related to EGFR over-expression and may be contribute to erlotinib-resistance of glioblastoma cells." (PMID 32592373, 2020). "First, a recent work using a different CRISPRko library in glioblastoma stem cells treated with TMZ also revealed MMR genes as top gene candidates, and more recently, using U87MG and U87MG, EGFRvIII cells revealed that E2F6 controls TMZ resistance in EGFR mutates cells." (PMID 33271924, 2020). "In neuronal glioblastoma (GBM) stem cells, an EGFR inhibitor [bevacizumab or temozolomide (TMZ)] combined with a late-stage autophagy blocker, chloroquine (CQ), improves drug toxicity, leading to the impairment of GBM CSC proliferation and survival." (PMID 32391363, 2020).
glioblastoma (continued). "In addition, comparable to EGFR overexpressing glioblastoma, low autophagy activity, as observed in EI24 low cells, could increase the dependence of PDAC on residual autophagy." (PMID 32878084, 2020). "We aimed to evaluate the preclinical efficacy of GC1118, a novel anti-epidermal growth factor receptor (EGFR) monoclonal antibody (mAb), against glioblastoma (GBM) tumors using patient-derived xenograft (PDX) models." (PMID 33142709, 2020). "Lastly, we found that miR-221 is potentially linked with the observed lack of EGFR expression in treatment-resistant glioblastoma cells and is may be a key regulator in glioblastoma resistance." (PMID 33082482, 2020). "For example, magnetic iron-oxide NPs (IONPs, 10 nm) decorated with the epidermal growth factor receptor (EGFR) antibody cetuximab were targeted EGFRvIII-overexpressing glioblastoma (GBM) cells." (PMID 32168899, 2020). "Moreover, EGFR was important for glioblastoma cell growth and tumor initiation, though the potential upstream regulatory mechanism of EGFR in glioblastoma remains unknown." (PMID 32962742, 2020). "Given that our treatment resistant Glioblastoma cells have low EGFR levels and higher miR-221 expression compared to their treatment-sensitive counterparts we next aimed to establish whether miR-221 directly regulated EGFR expression and played a role in the observed treatment resistance." (PMID 33082482, 2020). "Furthermore, we found that lower-level EGFR expression is common in glioblastoma." (PMID 31903167, 2019). "Thus, inhibitors of EGFR are considered as a therapeutic option for glioblastoma." (PMID 31284441, 2019). "Thus, EGFR is considered as an important therapeutic target in glioblastoma." (PMID 31013819, 2019). "They observed that besides the mutations in signature oncogenes of glioblastoma (e.g., EGFR and phosphatidylinositol 3-kinase (PI3K)), more than 40% of patients had mutations among the chromatin-modifier genes, which play a major role in chromatin organization in glioblastoma pathology." (PMID 31013819, 2019). "We have successfully applied the model to identify the interconnections altered in the constitutive signaling of the mutated EGFR in glioblastoma multiforme (GBM) compared to EGF-dependent and wild-type EGFR (EGFRwt) signaling." (PMID 31386654, 2019). "However, glioblastoma is genetically a highly heterogeneous cancer, and several targets have been implicated in chemoresistance, including MGMT, isocitrate dehydrogenase (IDH) 1/2, and epidermal growth factor receptor." (PMID 30717309, 2019). "Three missense mutations within the EGFR ECD (P596L, G598 V, and A289V) were previously reported in glioblastoma (GBM)." (PMID 29455648, 2018). "Although EGFR inhibitors were efficacious on GBM cells in vitro, clinical trials performed to date have been disappointing at targeting EGFR in glioblastoma." (PMID 30514230, 2018). "Cells with EGFR gene amplification preferentially move to the infiltrating edges of glioblastoma, indicating that EGFR signaling confers a special advantage for GBM progression and migration." (PMID 30514230, 2018).
glioblastoma (continued). "Epidermal growth factor receptor (EGFR) gene alterations and amplification are frequently reported in cases of glioblastoma (GBM)." (PMID 30305059, 2018). "However, it has been shown that microglia cells also express the membrane-spanning EGF precursor which might also be capable of activating EGFR signaling in glioblastoma cells in a contact-dependent manner." (PMID 29389898, 2018). "Thus, it can be hypothesized that glioblastomas bearing EGFR amplification favor the development of EGFRvIII or other EGFR mutants." (PMID 30279357, 2018). "Interestingly, a study that evaluated EGFR inhibition as a means to prime tumor vasculature for efficient delivery of chemotherapy showed that in glioblastoma patients, a 2-day pulse of high dose (5,250 mg/day) lapatinib given through twice daily dosing was well tolerated." (PMID 29293494, 2018). "Interestingly, a recent preclinical study provided evidence that chimeric antigen receptor (CAR)-engineered natural killer (NK) cells able to target wild-type EGFR and EGFRvIII markedly enhance the killing of glioblastoma cell lines and patient-derived glioblastoma stem cells." (PMID 30279357, 2018). "Indeed, EGFR amplification was identified in 17 cases (26.15%) of glioblastomas." (PMID 28785587, 2017). "Moreover, the T2 MR relaxation time of EGFR-SPIO nanoparticles could be used for successfully identifying glioblastoma cells with elevated EGFR expression in vitro and distinguishing U-251 cells from U-87MG cells, which have low EFGR expression." (PMID 29166921, 2017). "The oncogenic mutation denoted as EGFRvIII (EGFR verIII) is found in approximately 40% of high-grade human gliomas (glioblastoma multiforme (GBM)) with wild-type EGFR amplification." (PMID 29140271, 2017). "Aberrant expression of epidermal growth factor receptor (EGFR) and/or the ligand-independent EGFR mutant EGFRvIII (a product of a genetic deletion resulting in loss of exons 2-7 in the mRNA) is a frequent phenomenon in glioblastoma, driving growth and migration of tumor cells." (PMID 28074274, 2017). "We aimed to correlate 5-ALA induced fluorescence with the expression of epithelial growth factor receptor (EGFR) and its constitutively active version EGFRvIII in different glioblastoma (GBM) cell lines." (PMID 28500562, 2017). "The EGFR pathway is one of the most significant signaling pathways in glioblastoma, and EGFR is among the major genetic factors affecting the pathogenesis and prognosis of GBM." (PMID 28049521, 2017). "Aberrant EGFR signaling in GBM mediates STAT3 transcriptional activation to promote tumorigenesis, progression and invasion of glioblastoma." (PMID 29129908, 2017). "However, we note that this may be an underestimate, as many of the sequencing assays used in project GENIE fail to detect gene rearrangements and large deletions, such as the EGFR type III variant, frequently found in glioblastoma." (PMID 29371993, 2017). "Thus, EGFR represents a prime therapeutic target for glioblastoma." (PMID 29371993, 2017). "Epidermal growth factor receptor (EGFR) and the mutant EGFRvIII are major focal points in current concepts of targeted cancer therapy for glioblastoma multiforme (GBM), the most malignant primary brain tumor." (PMID 28629170, 2017). "Therefore, glioblastoma is naturally resistant to EGFR‐TKI treatment." (PMID 28097086, 2017). "To examine how IgG subclass may affect antibody-mediated cellular phagocytosis (ADCP) effects and CD47-Sirp disruption-induced phagocytosis, we treated glioblastoma cells with an IgG1-antibody against an unrelated target, epidermal growth factor receptor (EGFR, cetuximab)." (PMID 27092773, 2016).
glioblastoma (continued). "Abnormal activation of the epidermal growth factor receptor (EGFR) due to a deletion of exons 2-7 of EGFR (EGFRvIII) is a common alteration in glioblastoma (GBM)." (PMID 27738329, 2016). "This raises the question whether general PTP profiles are influenced by characteristic genetic alterations associated with lower grade glioma (frequently IDH-mutant) or glioblastoma (e.g. EGFR amplification; PTEN deletion) or rather reflect the tumor pathogenesis, including cell of origin." (PMID 27586084, 2016). "Therefore, we propose a hypothesis in which TAZ potentiates EGFR signaling, accelerates the cell cycle, and promotes cell proliferation, eventually leading to the progression of glioblastoma." (PMID 27167112, 2016). "A recent study by Labussiere and colleagues also demonstrated that combined analysis of TERTp, EGFR and IDH1/2 defined distinct prognostic classes in glioblastomas, with the absence of both EGFR amplification and TERTp mutation associating with longer survival in patients with glioblastomas." (PMID 26369702, 2015). "The alteration of the epidermal growth factor receptor (EGFR)-driven signaling network is a characteristic feature of glioblastomas (GBM), and its inhibition represents a treatment strategy." (PMID 25885672, 2015). "Notably, aberrant Akt activation is a poor prognostic factor for glioblastoma of all stages and contributes to resistance to first-generation single-agent targeting therapy such as gefitinib, a tyrosine kinase inhibitor clinically used for patients with glioblastoma with EGFR over-activation." (PMID 26265437, 2015). "Our studies revealed that HDAC9 promotes GBM growth via TAZ-mediated EGFR pathway activation, and provide the evidence for promising target for the treatment of glioblastoma." (PMID 25760078, 2015). "Dysregulated EGFR in glioblastoma may inactivate the key autophagy protein Beclin1." (PMID 25821789, 2015). "The genomic profiling of the GB samples included in our study confirmed the presence of common glioblastoma alterations reported in previous studies: loss/partial loss of chromosome 10, polysomy of chromosome 7, focal deletion of the CDKN2A/B and focal high-level amplifications of EGFR." (PMID 25940437, 2015). "Furthermore, a previous study found evidence of tumor PAI at the EGFR locus, one of our candidate amplification loci, through in silico analysis of glioblastoma data from TCGA, with preferential amplification of a SNP allele (rs13222385, G) that was associated with increased EGFR expression." (PMID 26575185, 2015). "EGFR gene amplification is present in ~40% of glioblastoma multiforme (GBM), with EGFRvIII almost exclusively expressed in EGFR amplified tumors." (PMID 25658924, 2015). "First, we focused on cancer types known to have frequent activating mutations in KRAS or EGFR: colorectal adenocarcinoma (COAD) and glioblastoma multiforme (GBM), respectively." (PMID 26047463, 2015). "For example, in glioblastoma multiforme (GBM) TKIs have been tested that target the epidermal growth factor receptor (EGFR)." (PMID 26136341, 2015). "Furthermore EFEMP1 can act on other pathways, including EGFR which could also convey resistance to glioblastoma cells and could explain that only partial sensitization to TMZ treatment is observed upon Notch inhibition." (PMID 24495907, 2014). "Additionally, EGFR amplification was enriched in Classical glioblastomas." (PMID 24755548, 2014). "Thus, we tested the hypothesis that the lowered EGFR signaling in G-CIMP+ glioblastomas was related to lowered EGFR expression in these tumors." (PMID 25277177, 2014). "Whether microRNAs can impact the therapeutic effects of EGFR inhibitors in glioblastoma is unknown." (PMID 24650032, 2014). "However, the molecular mechanisms underlying the EGFR/NF-κB signal pathway in glioblastomas have not been yet been fully elucidated." (PMID 25215581, 2014).